AASDH (aminoadipate-semialdehyde dehydrogenase)
Description:
Covalently binds beta-alanine in an ATP-dependent manner to form a thioester bond with its phosphopantetheine group and transfers it to an, as yet, unknown acceptor. May be required for a post-translational protein modification or for post-transcriptional modification of an RNA.
Synonyms: ACSF4; NRPS998; LYS2; NRPS1098
Tractability: PROTAC: ubiquitination databases record sites on it.
Gene: Protein-coding gene on chromosome 4 (56,337,994 to 56,387,523, reverse strand). Ensembl gene ENSG00000157426.
Gene Ontology:
Biological process: fatty acid metabolic process
Genetic constraint (gnomAD): Loss-of-function variants: 68 observed, 87.96 expected, observed/expected ratio (o/e) 0.77, 90% interval 0.63 to 0.95. The upper end of that interval is the gene's LOEUF score, 0.95, which puts it in group 4 of 6, group 1 being the genes least tolerant of losing a copy. Missense variants: 1,114 observed, 1,200 expected, observed/expected ratio (o/e) 0.93, 90% interval 0.88 to 0.98. Synonymous variants: 366 observed, 438.45 expected, observed/expected ratio (o/e) 0.83, 90% interval 0.76 to 0.91.
Homologues: Orthologues: chimpanzee AASDH (99% identical), macaque AASDH (96% identical), dog AASDH (85% identical), pig AASDH (81% identical), guinea pig AASDH (81% identical), rabbit AASDH (76% identical), mouse Aasdh (73% identical), rat Aasdh (72% identical), tropical clawed frog aasdh (51% identical), zebrafish aasdh (42% identical), Drosophila melanogaster Aasdh (25% identical), Caenorhabditis elegans W09D6.1 (20% identical). Paralogues in human: ACSF3 (10% identical), ACSF2 (9% identical), ACSS2 (9% identical), ACSS1 (9% identical), ACSM3 (8% identical), ACSM4 (8% identical), ACSM5 (8% identical), ACSS3 (8% identical), ACSM2B (8% identical), ACSM2A (7% identical), ACSM1 (7% identical), AACS (6% identical), and 1 more.
Diseases named in the same sentence as AASDH in open-access papers:
AASDH is named in the same sentence as 2 diseases in open-access papers, as found by Europe PMC text mining. Sharing a sentence is not in itself a finding about the gene and the disease. The quoted sentences say what the papers report.
hepatocellular carcinoma (1 paper, 2022). A malignant tumor that arises from hepatocytes. "As a category of ACS isozymes, members of ACS family (AACS, ACSF2-3, AASDH) participate in lipid metabolism; however, their expression patterns, regulatory mechanisms and effects in hepatocellular carcinoma (HCC) are poorly understood." (PMID 36205594, 2022).
tumor (1 paper, 2022). "Then, the expression level of AACS (p < 0.05) and ACSF2 (p < 0.05) were remained significantly raised in HCC tissues according to GEPIA database, but the expression level of AASDH was reduced in tumor tissues than in normal tissues." (PMID 36205594, 2022). "In addition, high expression of circ-AASDH was found to participate in the tumor size, clinical stage and regulate the expression level of E2F7 by sponging miR-140-3p, which involves in the malignant progression of LUAD." (PMID 36205594, 2022).